THBS1 (thrombospondin 1)
Diseases named in the same sentence as THBS1 in open-access papers (continued):
Sharing a sentence is not in itself a finding about the gene and the disease.
disseminated candidiasis (2 papers, 2012 to 2015). Systemic candidiasis occurs when Candida yeast enters the bloodstream and may spread (becoming disseminated candidiasis) to other organs, including the central nervous system, kidneys, liver, bones, muscles, joints, spleen, or eyes. "Conversely, inhibitors of thrombospondin-1 may be useful drugs to improve patient recovery from disseminated candidiasis." (PMID 23144964, 2012). "Thus, thrombospondin-1 enhances the pathogenesis of disseminated candidiasis by creating an imbalance in the host immune response that ultimately leads to reduced phagocytic function, impaired fungal clearance, and increased mortality." (PMID 23144964, 2012). "Here, we show that mice lacking thrombospondin-1 have an advantage in surviving disseminated candidiasis and more efficiently clear the initial colonization from kidneys despite exhibiting fewer infiltrating leukocytes." (PMID 23144964, 2012).
Down syndrome (2 papers, 2010 to 2023). "Reduced thrombospondin-1 levels have been reported in Down syndrome and sporadic AD brains." (PMID 37055866, 2023).
endometrial cancer (2 papers, 2022). Primary or metastatic malignant neoplasm involving the endometrium (mucous membrane that lines the endometrial cavity). "As in the mouse model, the number of capillaries is higher in endometrial cancer with high THBS1 expression levels, suggesting that elevated THBS1 expression is associated with an angiogenic phenotype in endometrial cancer." (PMID 35409214, 2022).
endotoxemia (2 papers, 2016 to 2019). "Therefore, thrombospondin-1 and its receptor CD47 may be useful targets for limiting the pro-inflammatory effects of lipopolysaccharide and for treating endotoxemia." (PMID 26813769, 2016).
fatty liver (2 papers, 2022). "For example, the serum level of thrombospondin-1 (TSP1) in patients with fatty liver was increased before treatment, but the serum TSP1 level was decreased after hepatic fat-lowering therapy." (PMID 36263163, 2022). "THBS1 bound to many transforming growth factors and cell surface receptors to regulate cellular adhesion, platelet aggregation, angiogenesis, and hepatic steatosis." (PMID 35627183, 2022).
fibrosarcoma (2 papers, 2020 to 2023). A malignant mesenchymal fibroblastic neoplasm affecting the soft tissue and bone. "Yet another angiogenesis-regulating molecule, thrombospondin-1 (TSP-1), is secreted by a fibrosarcoma primary tumor model in mice and has been proposed to inhibit angiogenesis in the cornea and the growth of metastasis." (PMID 37222464, 2023).
gastric adenocarcinoma (2 papers, 2020 to 2021). "However, the hotspot mutation G203Afs∗13 of THBS1 was found in three patients with STAD (stomach adenocarcinoma), which encodes a truncated form." (PMID 34804159, 2021). "We identified THBS1, FN1, CALM1, COL4A1, CTGF, and IGFBP5 as potential inflammation-related targets for the treatment of gastric adenocarcinoma." (PMID 32801999, 2020).
gout (2 papers, 2021 to 2023). A condition characterized by painful swelling of the joints, which is caused by deposition of urate crystals. "Histone H2A, Histone H2B and THBS1 are potential candidate genes for novel biomarkers in discriminating gout attack from AHU or RG, providing new theoretical insights for the prognosis, treatment, and management of gout process." (PMID 34635120, 2021). "Histone H2A, Histone H2B and THBS1 might be the strongest influential regulator to maintain the balance and stability of the gout process." (PMID 34635120, 2021). "So THBS1 negatively regulates disease by acting indirectly on other gout related proteins." (PMID 34635120, 2021). "Among these proteins, histone H2A, histone H2B and THBS1 might be the strongest influential regulator to maintain the balance and stability of the gout process and complement and coagulation cascades is one of the main functional pathways in the mechanism of gout process." (PMID 34635120, 2021). "A possible explanation for this might be that THBS1 is not directly involved in the course of gout." (PMID 34635120, 2021).
hantavirus infection (2 papers, 2016 to 2022). "In this report, we have demonstrated the in vitro suppression of THBS1 transcription in endothelial cells through hantavirus infection." (PMID 27486439, 2016). "We additionally show that hantavirus infection reduces THBS1 protein accumulation in the extracellular matrix of endothelial cells." (PMID 27486439, 2016). "With this in mind, we sought to determine if hantavirus infection and replication affects THBS1 accumulation in cultured HUVEC." (PMID 27486439, 2016). "In the present study, we demonstrate that in vitro hantavirus infection of endothelial cells suppresses transcription of THBS1 and its subsequent accumulation in the extracellular matrix." (PMID 27486439, 2016). "Our data suggests that hantavirus infection directly influences the expression and accumulation of THBS1, an endothelial cell protein with putative roles in cell adhesion, platelet aggregation, and the regulation of fibrinolysis." (PMID 27486439, 2016). "As previously reported, THBS1 plays a key role in pathophysiology of hantavirus infection." (PMID 35774982, 2022). "Our data suggest that hantavirus infection activates c-Jun; therefore, it is possible that TNFα may synergizes hantavirus-triggered activation of transcription factors including those involved in THBS1 accumulation." (PMID 27486439, 2016).
HCMV infection (2 papers, 2010 to 2025). "We confirmed alterations in expression levels at the protein level for the classic TEAD1 targets Thrombospondin 1 (THBS1) and Cellular Communication Network Factor 1 (CCN1), both of which were substantially downregulated upon HCMV infection." (PMID 40928347, 2025).
influenza (2 papers, 2022 to 2025). An acute viral infection of the respiratory tract, occurring in isolated cases, in epidemics, or in pandemics; it is caused by serologically different strains of viruses (influenzaviruses) designated A, B, and C, has a 3-day incubation period, and usually lasts for 3 to 10 days. "This analysis revealed a significant enrichment of THBS1 and NR4A1 in the influenza samples, which are both genes that have been shown to be engaged in response to influenza-induced lung injury." (PMID 35233546, 2022).
intestinal tumors (2 papers, 2022 to 2023). "In this study, we demonstrated that THBS1 produced by BM-derived monocyte-like cells contributes to progression of aggressive intestinal tumors by suppressing cytotoxic immune activity, particularly at metastatic sites." (PMID 37749092, 2023). "This study reveals the THBS1-YAP axis as the mechanistic link mediating paracrine interactions between epithelial cells in intestinal tumours." (PMID 35543624, 2022). "(A, C) Representative section of Apc mutant intestinal tumours analysed by single-molecule fluorescence in situ hybridisation (smFISH) for Thbs1 (pThbs1, red dots) and Lgr5 (pLgr5, green dots in A) or the YAP target Sca1 (pSca1, green dots in C)." (PMID 35543624, 2022). "Our results, corroborated by consistent observations in mouse and human intestinal tumours, uncovered a novel function for the secreted multidomain glycoprotein THBS1 in affecting the behaviour of normal epithelial cells surrounding a nascent tumour." (PMID 35543624, 2022). "(E) Correlation of the number of RNA molecules (dots/mm2) detected by single-molecule RNA fluorescence in situ hybridisation (smRNA FISH) for the YAP target CTGF and Thbs1 in mouse intestinal tumours." (PMID 35543624, 2022).
invasive carcinoma (2 papers, 2022 to 2024). A carcinoma that is not confined to the epithelium, and has spread to the surrounding stroma. "Other differentially expressed transcripts include S100A7, LCN2, CXCL14, and CD207 (decreasing expression from premalignant lesions to invasive carcinoma), as well as IDO1, IL6, IL8, THBS1, and FN1 (increasing expression from premalignant lesions to invasive carcinoma)." (PMID 38706595, 2024).
kidney failure (2 papers, 2025). An acute or chronic condition that is characterized by the inability of the kidneys to adequately filter the blood. "Furthermore, miR-221 inhibits latent TGF-β1 activation through targeting thrombospondin-1 (THBS1), a key activator of TGF-β1, thereby attenuating kidney failure-induced cardiac fibrosis." (PMID 41369385, 2025).
laryngeal squamous cell carcinoma (2 papers, 2019 to 2025). A squamous cell carcinoma that arises from the larynx. "Consistent with our results, inhibition of THBS1 induced by DNA hypermethylation shares an association with tumor progression in laryngeal squamous cell carcinoma." (PMID 31847842, 2019).
liver cirrhosis (2 papers, 2024). "One study showed that endogenous opioid levels increase with liver cirrhosis, a condition also associated with a significant increase in thrombospondin-1 (THBS-1) and Keap1, as well as a reduction in Nrf2." (PMID 38255895, 2024).
mastitis (2 papers, 2020). Inflammation of breast tissue during lactation or postpartum due to an obstructed duct or infection. "In summary, TMT analyses elucidated the role of A2M, Itgb2, Thbs1, Fn1, ITIH4 and other proteins in the host innate response to S. aureus-induced mastitis." (PMID 32365127, 2020).
medullary carcinoma of the thyroid (2 papers, 2020 to 2024). "THBS1 expression has been shown to be associated with poor prognosis in medullary thyroid carcinoma." (PMID 39404708, 2024).
medulloblastoma (2 papers, 2013 to 2020). A malignant, invasive embryonal neoplasm arising from the cerebellum. "A previous study demonstrated that downregulation of THBS1 was strongly associated with MYC-driven metastatic phenotype of medulloblastoma." (PMID 23768125, 2013). "Finally, we correlated their expression with patient outcome finding that altered VCAM1, TP63, ANKRD1, THBS1, and PTHLH levels correlated with lower patient survival in Group 4 medulloblastoma samples." (PMID 32316671, 2020). "Next, we moved our attention to genes already related to medulloblastoma based on the literature and validated some of them, such as POSTN, BOC, VCAM1, and TP63 among the downregulated genes and ANKRD1, THBS1, NRG1, PTHLH, and HBEGF among the upregulated ones in DAOY and D283Med cells." (PMID 32316671, 2020).
oral submucous fibrosis (2 papers, 2024 to 2025). "This recreation of OSF revealed the regulatory role of thrombospondin-1 (THBS1) and, in particular, that stromal thrombospondin 1 suppresses angiogenesis in Oral Submucous Fibrosis." (PMID 40565504, 2025).
prediabetes (2 papers, 2024 to 2025). "Evidence suggests that THBS1 contributes to adipose tissue inflammation and metabolic dysregulation, explaining its elevated levels in prediabetes." (PMID 40162315, 2025). "In prediabetes, the THBS1 pathway could significantly aggravate these complications." (PMID 39050565, 2024). "Pulmonary vascular function, including the roles of nitric oxide (NO), prostacyclin (PGI2), endothelin-1 (ET-1), thromboxane A2 (TxA2) and thrombospondin-1 (THBS1), is discussed in the context of T2DM and prediabetes." (PMID 39050565, 2024). "Nano-LC/MS in SRM mode (SRM-MS) identified positive correlations between MASP1, THBS1, GPLD1, and prediabetes, while ApoA-IV showed a negative association." (PMID 40162315, 2025). "Elevated blood glucose in prediabetes could lead to the formation of AGEs, which might bind to the RAGE and upregulate THBS1 expression, further impairing endothelial function." (PMID 39050565, 2024).
psoriasis (2 papers, 2013 to 2019). An autoimmune condition characterized by red, well-delineated plaques with silvery scales that are usually on the extensor surfaces and scalp. "In psoriasis, hypervascular skin lesions over expressed the angiogenic polypeptide IL8 and under expressed the angiogenic inhibitor thrombospondin 1 (TSP-1)." (PMID 23983401, 2013).
pulmonary edema (2 papers, 2021 to 2025). Accumulation of fluid in the lung tissues causing disturbance of the gas exchange that may lead to respiratory failure. "That is probably because THBS1 can regulate vascular permeability, and its decreased expression may lead to increased vascular permeability, further aggravating pulmonary edema and worsening lung disease." (PMID 40182927, 2025). "Compared to tTA controls, Thbs1 DTG mice also displayed a significant reduction in fractional shortening and increased incidence of pulmonary edema at 6–7 weeks of age." (PMID 34168130, 2021).
renal cell carcinoma (2 papers, 2011 to 2025). "In a more recent investigation, an MS-based proteomics workflow for identifying differentially abundant proteins in renal cell carcinoma (RCC) demonstrated elevated levels of enolase 2 (ENO2) and thrombospondin-1 (TSP1) in tumor TIF." (PMID 21980378, 2011).
scleroderma (2 papers, 2017 to 2019). Scleroderma is a rare autoimmune connective tissue disorder characterized by abnormal hardening of the skin and, sometimes, other organs. "Previous studies have demonstrated that thrombospondin 1 in scleroderma fibroblasts can activate TGF-β to stimulate ERK-dependent collagen contraction." (PMID 31653900, 2019).
steatosis (2 papers, 2021 to 2025). Increased lipid within the cytoplasm of cells. "The heatmap shows the relative expression levels of the four genes (AKR1B10, FABP4, GNMT, and THBS1) in normal, steatosis, and steatohepatitis tissues across the three training datasets." (PMID 39781352, 2025). "Eventually, we determined 10 hub genes (Down-regulated genes: MYC, TGFB3, ADAMTS1, THBS1, RASD1, PCDH20; Up-regulated genes: MAMDC4, CYP7A1, GINS2, and PDLIM3) related to NAS and steatosis." (PMID 34777484, 2021).
Thrombocytopenia (2 papers, 2021 to 2025). A reduction in the number of circulating thrombocytes. "Platelets release substances like thrombospondin-1 that counter lung injury and, as reported in other patient groups, we found that thrombocytopenia correlated with increased mortality in this Afro Caribbean cohort." (PMID 34684107, 2021).
uveitis (2 papers, 2024 to 2025). An inflammatory process affecting a part of or the entire uvea. "Moreover, Th17‐related monocytes that highly express lncRNA XIST, CLEC10A, CX3CR1, and THBS1, which are considered critical alarmins that induce inflammation, may be the most feasible hub genes for AS‐associated uveitis and have been found to participate in Th17 cell differentiation." (PMID 39473904, 2024). "The abundance of THBS1 was 3.6-fold higher in healthy RMG compared to RMG from uveitis cases." (PMID 40001591, 2025). "Among these, the Major Histocompatibility Complex (MHC) class II and the enzyme Arginase 1 (ARG1) were significantly enriched in RMG from uveitis-affected horses, whereas Mannose Receptor C-type 2 (MRC2) and its interactor Thrombospondin 1 (THBS1) were more abundant in healthy RMG." (PMID 40001591, 2025).
abortion (1 paper, 2021). the ending of pregnancy by removing a fetus or embryo before it can survive outside the uterus. "Decreased THBS1 expression in decidua macrophages was associated with unexplained recurrent spontaneous abortion." (PMID 34831106, 2021).
acute-on-chronic liver failure (1 paper, 2024). Acute-on-chronic liver failure (ACLF) is an extreme condition during the natural history of chronic HBV infection, with a relatively high short-term mortality. "The key role of thrombospondin 1 (THBS1) in the pathogenesis of acute-on-chronic liver failure (ACLF) is unclear." (PMID 38439091, 2024).
adenomyosis (1 paper, 2025). The growth of endometrial tissue inside the muscular wall of the uterine corpus. "There exists only one study so far where increased THBS1 gene expression in adenomyosis is reported." (PMID 41272701, 2025). "On comparing adenomyosis patients with controls, significant differences were observed in the expression of MMP9, MMP11, SERPINA1, IGFBP5, and TIMP1 (p < 0.05); however, MMP7 and THBS1 remained comparable." (PMID 41272701, 2025).
aging (1 paper, 2024). A developmental process that is a deterioration and loss of function over time. "In this study, we identified thrombospondin-1 (THBS1) and fibromodulin (FMOD) as positive and negative regulators, respectively, of the TGF-β1-SMAD4 axis in human skin aging, based on in vitro and in vivo omics analyses and mathematical modeling." (PMID 38706856, 2024).
AIDS (1 paper, 2018). A syndrome resulting from the acquired deficiency of cellular immunity caused by the human immunodeficiency virus (HIV). "In contrast, the protein expression level of THBS1 was downregulated 1.8-fold (n = 14 patients, p < 0.05) in HIV/AIDS patient serum samples with TM infection compared to the TM-negative group." (PMID 30598657, 2018). "According to hierarchal clustering analysis and KEGG network analysis, the proteins Interleukin-1 receptor-like 1 (IL1RL1, 10.62-fold) and thrombospondin 1 (THBS1, 1.82-fold) were differentially expressed in HIV/AIDS patients between the TM-positive group and the TM-negative control group." (PMID 30598657, 2018).
and neck cancer (1 paper, 2024). "and neck cancer (HNC), the invasion-associated molecules LAMA3, LAMC2, THBS1, IGF1R, PDGFB, and transforming growth factor β1 can serve as prognostic indicators or molecular therapeutic targets to improve the survival rates of HNC." (PMID 38877482, 2024).
Aortic dissection (1 paper, 2025). Aortic dissection refers to a tear in the intimal layer of the aorta causing a separation between the intima and the medial layers of the aorta. "Furthermore, the high expression of some factors released by PLTs such as PLT-derived growth factor B (PDGF-B) and Thrombospondin 1 (TSP1) in type A aortic dissection may also indicate the role of PLTs in the disease." (PMID 40336641, 2025).
aortic stenosis (1 paper, 2022). Aortic valve stenosis is a aortic valve disease caused by the incomplete opening of the aortic valve. "After this, we prioritized two proteins related to endoplasmic reticulum stress, thrombospondin-1 and endoplasmin, which have not been previously validated as markers for aortic stenosis, and analyzed them in a cell model and in plasma from human subjects." (PMID 35455758, 2022).
ascending aortic aneurysms (1 paper, 2022). "Maladaptive upregulation of Thbs1 results in disruption of elastin-contractile units and dysregulation of actin cytoskeletal remodeling, contributing to the development of ascending aortic aneurysms in vivo." (PMID 35432454, 2022).
autism (1 paper, 2022). Persistent deficits in social interaction and communication and interaction as well as a markedly restricted repertoire of activity and interest as well as repetitive patterns of behavior. "Furthermore, another study also suggested common variants of the THBS1 gene, encoding thrombospondin 1 protein, could be protective against autism and rare variants pose a genetic predisposition to autism." (PMID 36326357, 2022).
autoimmune disorders (1 paper, 2024). "Research has shown significant functions of thrombospondin-1 in regulating immune responses in autoimmune disorders." (PMID 38715599, 2024).
autoimmune uveitis (1 paper, 2025). An autoimmune form of uveitis (disease). "These proteins, especially MRC2 and THBS1, emerge as potential markers for assessing RMG activation, retinal immune balance, and the maintenance of ocular immune privilege in autoimmune uveitis." (PMID 40001591, 2025).
brain tumor (1 paper, 2021). "Immunofluorescence of mouse brain tumor tissue revealed the same results as IHC of THBS1 and MYH9." (PMID 34635636, 2021).